INS (insulin)
Diseases named in the same sentence as INS in open-access papers (continued):
Sharing a sentence is not in itself a finding about the gene and the disease.
coronary artery calcification (8 papers, 2018 to 2025). Calcification of the coronary artery, used as a measure of coronary atherosclerosis, a risk factor for myocardial infarction. "We targeted global and region-specific variations using insulin sensitivity (IS) and coronary artery calcifications (CACs) as CV risk factor in T2D patients." (PMID 36834662, 2023). "Fasting insulin, not glucose nor HbA1c, is associated with coronary artery calcification and its progression." (PMID 29593575, 2018).
diabetic autonomic neuropathy (8 papers, 2015 to 2026). Autonomic neuropathy that is caused by diabetes mellitus. "Proband 2 exhibited poor islet function at early onset, accompanied by diabetic autonomic neuropathy and peripheral neuropathy, and glycemic control remained unsatisfactory despite insulin therapy." (PMID 41890190, 2026). "Although it has been suggested that diabetic autonomic neuropathy damages the vagus nerve, which physiologically controls the heart rate and the secretion of insulin from beta cells, autonomic dysfunction in the wake of insulin resistance is also possible." (PMID 29681953, 2018). "These may include the lack of trophic action of insulin, glucagon, and somatostatin, autoimmune damage to the pancreas, and the presence of autonomic diabetic neuropathy, which can impair the entero-pancreatic reflex." (PMID 38398492, 2024).
enteroviral infection (8 papers, 2019 to 2025). "Data on association between enteroviral infection, NK cells, insulitis, autoimmunity and destruction of insulin-producing pancreatic islet beta cells in human are scarce but relevant." (PMID 32630332, 2020). "These enterovirus infections can then induce beta pancreatic cell death and decrease insulin synthesis and secretion." (PMID 35930583, 2022). "Both acute and persistent enterovirus infections have been shown to affect the functions of the host cell, inducing β cell death, decreasing insulin mRNA expression and insulin secretion, and disrupting the Golgi apparatus." (PMID 34557158, 2021). "Enteroviral infections were reported to induce beta cell death, decrease in insulin mRNA expression and insulin secretion and disruption of Golgi apparatus." (PMID 31754894, 2019).
fragile X syndrome (8 papers, 2020 to 2024). A genetic syndrome caused by mutations in the FMR1 gene which is responsible for the expression of the fragile X mental retardation 1 protein. "Igf2 codes IGF2, which is one member of the insulin signaling pathway and its deficiency can lead to serious cognition dysfunction and it is involved in impaired cognition in Fragile X syndrome." (PMID 33040050, 2020). "The signaling pathways of these upregulated OCRGs included regulation of autophagy, adaptive immune system, Fragile X syndrome, insulin secretion lipid transport, and organic hydroxy compound metabolic process." (PMID 34368262, 2021).
glomerular disease (8 papers, 2015 to 2026). "Targeting MCT1 and lactate metabolism may offer a novel therapeutic strategy for glomerular diseases that are characterized by insulin resistance and metabolic dysregulation." (PMID 41565972, 2026). "This mimics what is seen in an animal model of VEGF-A overexpression in which glomerular disease was induced and an in vitro model of insulin sensitivity where increased VEGF was seen in response to insulin treatment." (PMID 30207171, 2018).
hypocortisolism (8 papers, 2009 to 2025). "However, an insulin tolerance stress test resulted in a finding of hypocortisolemia among the RA patients relative to controls, and similar results were obtained using a combined stressor of exercise, cold pain, and mental stress." (PMID 19413909, 2009). "Prevalence of hypocortisolism relying on dynamic and nondynamic testing was 15% (95% CI: 6%–28%, 5 studies, 205 patients, 57.5% males) and including only studies using the insulin tolerance tests 24% (95% CI 16%–33%, 2 studies, n = 97 patients)." (PMID 31511863, 2020). "However, in cases of clinical signs of hypocortisolism, we recommend assessing the hypothalamic-pituitary-adrenal axis using the metyrapone test or, in the absence of contraindications, the insulin tolerance test." (PMID 32877518, 2020).
Intellectual disability (8 papers, 2015 to 2025). "People with intellectual disabilities who use insulin, require reasonable adjustments to education, support, and a person‐centred approach to facilitate supported self‐management." (PMID 35983585, 2022). "Despite barriers, attempts to reduce inequalities for people with intellectual disabilities who use insulin were evident throughout the data." (PMID 35983585, 2022). "This can involve seizures, intellectual disability and, due to the role of Cav1.3 for aldosterone and insulin secretion), also with (often transient,) endocrine symptoms." (PMID 31921405, 2020). "Considering the emerging importance of Drosophila models of memory in understanding intellectual disability and cognitive function, we sought to understand the role of InS in memory formation, more specifically protein synthesis dependent memory." (PMID 25805973, 2015). "However, Gregory's (2019) project aimed to improve service standards for people needing support (including those with intellectual disabilities who use insulin), illustrating that there are creative solutions to managing challenges." (PMID 35983585, 2022). "Insulin pump therapy can be complex, requiring a high level of self‐management, but as technology evolves it may become more accessible to people with intellectual disabilities." (PMID 35983585, 2022). "However, providing a person with an intellectual disability such as Pat, with medicines, including insulin, alone is unlikely to be sufficient to achieve his treatment goals." (PMID 33494475, 2021).
male infertility (8 papers, 2014 to 2025). The inability of the male to effect fertilization of an ovum after a specified period of unprotected intercourse. "Testicular dysfunction arising from perturbed glucose metabolism, and characterized by impaired FSH and insulin signaling, is a major contributor to male infertility in T2D." (PMID 41047805, 2025). "Assessment of the effect of BV on T2DM and the consequence of male infertility is crucial to identify the regulatory role of BV on glucose and insulin levels and improve male infertility." (PMID 36341058, 2022). "Patients were subdivided into 3 groups: control (n=8,fertile women with male infertility history), insulin resistant (IR) PCOS (n=7), and insulin sensitive (IS) PCOS (n=8)." (PMID 30507086, 2019). "In a prospective study involving nonobese, nonhyperandrogenemic patients with PCOS undergoing IVF, it was observed that serum insulin and HOMA-IR were significantly increased in PCOS patients compared to those with male infertility and unexplained infertility." (PMID 40441206, 2025). "Therefore, we propose that the quassinoid-containing E. longifolia extract affects male infertility by suppressing AHS expression, which indirectly increases insulin sensitivity and testosterone levels in accordance with our previous findings." (PMID 26441666, 2015).
mastitis (8 papers, 2017 to 2025). Inflammation of breast tissue during lactation or postpartum due to an obstructed duct or infection. "Other metabolites and bioactive small molecules, such as insulin, cortisol, and adipokines (e.g., leptin and adiponectin), have also been associated with the development of mastitis." (PMID 41139776, 2025). "The stress response associated with mastitis, characterized by elevated cortisol levels, can impair the insulin sensitivity and exacerbate the development of ketosis." (PMID 39456911, 2024). "Although increased isoleucine and valine have been shown to impair hepatic insulin sensitivity and ketogenesis, potentially facilitating obesity-associated metabolic syndrome their roles in the pathogenesis of microbial dysbiosis-induced mastitis remain unclear." (PMID 41139776, 2025). "The statistically significant effect of mastitis on insulin was also observed prior to IMI; thus, it cannot be considered biologically relevant." (PMID 28740504, 2017). "Administration of TZD to lactating dairy goats undergoing subclinical mastitis had a relatively modest effect on milk yield and components and on overall metabolism with a possible temporary decrease on insulin sensitivity which was improved by TZD treatment." (PMID 28740504, 2017). "Although the role of C2CD4A in insulin secretion could theoretically be linked with milk-production-related traits, C2CD4A most likely contributes to the development of mastitis through its involvement in inflammation-related processes." (PMID 37685039, 2023).
metastatic disease (8 papers, 2015 to 2026). "In both studies, the patients had metastatic disease prior to the diagnosis of MHs, and insulin secretion related to worse prognosis, compared to other hormonal syndromes." (PMID 41561059, 2025). "Of these, 14 were preclinical studies of dietary strategies that demonstrated improvements in insulin levels, inhibition of metastasis, and/or reduction in metastatic disease burden in animal models." (PMID 36079800, 2022). "In summary, each of the insulin-lowering diets CR, KD, and IF strategies have shown benefit in preclinical models in reducing formation of metastases or decreasing metastatic disease burden." (PMID 36079800, 2022). "Of these, 14 were preclinical studies of dietary strategies that demonstrated improvements in insulin levels, inhibition of metastasis, and/or reduction of metastatic disease burden in animal models." (PMID 36079800, 2022). "The ultimate goal of the study was to assess the role of insulin and insulin-like growth factors in the proliferation, growth and migration of primary and metastatic tumor derived renal cancer cells." (PMID 30929166, 2019). "No cells in the metastatic tumors stained positive for insulin, somatostatin, or pancreatic polypeptide Y." (PMID 26192435, 2015). "The patient's condition deteriorated despite intravenous insulin and potassium, and a brain MRI was positive for central pontine ODS without evidence of metastatic disease." (PMID 40213725, 2025).
neutropenia (8 papers, 2007 to 2025). A decrease in the number of neutrophils found in the blood. "It is highly unlikely metformin or insulin induced the patient’s neutropenia as he has taken these medications for decades due to his chronic diabetes mellitus." (PMID 32448188, 2020). "Pair comparison analysis was performed to highlight possible correlations between drug treatment, insulin independence, induction treatments, and neutropenia/lymphopenia." (PMID 27285580, 2016). "Thus, it is postulated that in the presence of mild neutropenia, whose function is inhibited by effect of insulin excess, the bacillus was able to find a port of entry, probably via micro-abrasions of the bowel mucosal lining." (PMID 17967202, 2007).
Oligomenorrhea (8 papers, 2017 to 2025). Infrequent menses (less than 6 per year or more than 35 days between cycles). "Associations were attenuated for total T with further adjustments for smoking, physical activity, menstrual status, oral contraceptive/hormone (OCHM) use, insulin level, oligomenorrhea, and age at menarche, but remained statistically significant for free T and SHBG." (PMID 38213908, 2024).
partial lipodystrophy (8 papers, 2012 to 2023). Loss and redistribution of subcutaneous and/or visceral adipose tissue from specific regions of the body. "However, the loss of perigonadal fat in mice with partial lipodystrophy impaired insulin sensitivity." (PMID 36835312, 2023). "This controversy suggested that the metabolic condition of tissues other than the perigonadal depot was critical for whole-body insulin sensitivity in partial lipodystrophy." (PMID 36835312, 2023). "In mice with partial lipodystrophy, the inguinal fat-dependence index abnormally increased to 4.55-fold owing to the decrease in insulin sensitivity of perigonadal fat, reflecting the increased workload of inguinal fat." (PMID 36835312, 2023). "The Ddb1-AKO mice showed higher plasma levels of insulin and free fatty acids and significantly elevated liver triglyceride content, resembling the phenotype of partial lipodystrophy." (PMID 39872690, 2022). "Familial partial lipodystrophies (FPLD) are clinically heterogeneous disorders characterized by selective loss of adipose tissue, insulin resistance and metabolic complications." (PMID 22938045, 2012). "Thus, the improvement of adipose function in residual fat is a strategy for maintaining insulin sensitivity in patients with partial lipodystrophy." (PMID 36835312, 2023). "Third, while the beneficial effect of thiazolidinediones, one of very few drugs that clearly improve insulin sensitivity, was recognized before the discovery of PPARG mutations in patients with partial lipodystrophy, this link attests to the potential for human genetics to inform drug discovery." (PMID 34875679, 2022). "Mandibuloacral dysplasia type A (MADA) is a rare laminopathy characterized by growth retardation, craniofacial anomalies, bone resorption at specific sites including clavicles, phalanges and mandibula, mottled cutaneous pigmentation, skin rigidity, partial lipodystrophy, and insulin resistance." (PMID 22706480, 2012). "The liver and skeletal muscle of HFDTZD-fed PpargC/- mice also showed insulin-induced Akt phosphorylation similar to that of wild-type mice, suggesting that TZD is effective in normalizing the insulin sensitivity of the liver and skeletal muscle in mice with partial lipodystrophy." (PMID 36835312, 2023).
Polyhydramnios (8 papers, 2016 to 2026). The presence of excess amniotic fluid in the uterus during pregnancy. "The need for insulin administration showed an association with the higher/two-day BM dosage (p = 0.013) but not with maternal age, gestational age, body weight change, presence of hydramnios, or presence of thyroid disease." (PMID 32079162, 2020). "In two pregnancies with diagnosis of GDM, antenatal polyhydramnios were observed; one of them was treated with insulin." (PMID 39600958, 2024). "Eight patients in metformin group developed polyhydramnios whereas only 6 patients in insulin group showed polyhydramnios on growth scan." (PMID 27597988, 2016).
prostate tumour (8 papers, 2003 to 2026). "Alterations in insulin pathway genes, such as PTEN, FOXO, and PIK3CA, are mutated in up to 32%, 15%, and 11% of localized prostate tumors, respectively." (PMID 42192996, 2026). "And notably, an increased ratio of INSR/IGF1R expression has recently been described in prostate tumours and adjacent tissue, which suggests specifically that insulin signalling plays a key role in these tumours." (PMID 23573093, 2013). "We have shown that insulin acts directly on prostate tumour cells to increase intratumoural androgen production." (PMID 22548055, 2012). "A study of calorie restriction performed in mice showed a reduction in circulating IGF-I and insulin levels and deactivation of the PI3K/AKT pathway which resulted in prostate tumour growth inhibition." (PMID 32655839, 2020).
proteinopathies (8 papers, 2019 to 2024). "To investigate how this process impacts the interaction of SCGN with client proteins, we selected α-synuclein, an intrinsically unstructured protein prone to aggregation and implicated in proteinopathy, and insulin known to interact with SCGN." (PMID 35870554, 2022). "For example, mispaired disulfide bond formation contributes to proteinopathies such as cerebral autosomal dominant arteriopathy with subcortical infarcts and leukoencephalopathy, neonatal diabetes due to insulin gene mutations, and Ehlers-Danlos syndrome due to pro-alpha collagen mutations." (PMID 39303030, 2024). "When used on genetic modifiers of NDs, MLnet identifies the insulin signaling pathway and its constituents as potential elements that have broader relevance for proteinopathies." (PMID 37984409, 2023). "Common themes appear to emerge, most proteinopathies lead to reduced glycolysis, defective insulin signaling and impaired mitochondrial function." (PMID 35281504, 2022). "In this study, human insulin protein was used to analyze nanoparticle-induced proteinopathy in physiological conditions." (PMID 31417892, 2019). "Our finding suggests that members of the insulin pathway may have pathophysiological relevance for proteinopathies in general." (PMID 37984409, 2023). "Here, we analyzed human insulin aggregation as a model of nanoparticle-induced proteinopathy." (PMID 31417892, 2019). "T2DM is characterized as a metabolic disorder with defects in both insulin secretion and insulin action, and is also characterized by the presence of fibrillar amyloid deposits in the pancreatic islet of Langerhans, suggesting that T2DM is classified to protein-misfolding disease." (PMID 37305094, 2023).
Sensory neuropathy (8 papers, 2012 to 2023). Peripheral neuropathy affecting the sensory nerves. "These selected clinical risk factors were age, ACR, eGFR, HbA1c, insulin, sensory neuropathy, ACEIs or ARBs, CHD, retinopathy, TG, and LDL." (PMID 31882689, 2019). "Disrupting insulin signaling such as insulin-like growth factor-binding protein 2 (IGFBP2) in SCs, impairs myelination and induces a sensory neuropathy." (PMID 37594969, 2023).
stomach cancer (8 papers, 2017 to 2025). "H. felis was given to INSp-GAS (expression of gastrin under insulin promoter) transgenic mice, after which gastric tumor tissue was confirmed by histology after dissection out the formed tumor." (PMID 30844765, 2019). "INS, IGF1 and IGF2 CNV and relative overexpression were detected in 13% of gastric tumours." (PMID 34554347, 2022). "No insulin nor diabetic effect occurred in transplants of a mouse brain or stomach tumour." (PMID 5451575).
triple-negative breast carcinoma (8 papers, 2019 to 2024). An invasive breast carcinoma which is negative for expression of estrogen receptor (ER), progesterone receptor (PR), and human epidermal growth factor receptor 2 (HER2). "For the first time, the unique lipid metabolism of triple negative breast cancer was studied under tandem excess methionine and insulin conditions, and revealed key insights that span the metabolic, spatial, and biochemical dimensions." (PMID 35359364, 2022). "We aimed to dissect the specific impact of IR isoforms in modulating insulin signaling in triple negative breast cancer (TNBC) cells." (PMID 34831367, 2021).
adenovirus infection (7 papers, 2007 to 2025). "On the contrary, Aspg overexpression by adenovirus infection blunted insulin signaling in primary hepatocytes." (PMID 40760121, 2025). "After 30 minutes of incubation with 100 nM insulin, Akt was further activated 1.6 and 1.7-fold over the activation already induced by adenovirus infection." (PMID 17309805, 2007). "Therefore, we investigated the effect of adenovirus infection on insulin unresponsiveness by means of Akt activation in cultured cells." (PMID 17309805, 2007). "Thus, adenovirus infection may exacerbate β-cell destruction and subsequently decrease the secretion of insulin." (PMID 36291430, 2022). "When compared with adGFP-treated control animals, insulin-stimulated myocardial Akt phosphorylation and translocation of GLUT4 were severely blunted in hearts from adTNF-α-treated animals 1 wk post-adenovirus infection." (PMID 26659007, 2015). "Thus adenovirus infection increased basal Akt phosphorylation and insulin was not able to increase this further." (PMID 17309805, 2007). "Twenty five percent of cells were capable of activating the ectopic pancreatic insulin promoter upon PDX-1 infection; no signal was detected with control adenovirus infection." (PMID 22028850, 2011).